MOG (myelin oligodendrocyte glycoprotein)
Diseases named in the same sentence as MOG in open-access papers (continued):
Sharing a sentence is not in itself a finding about the gene and the disease.
neuromyelitis optica spectrum disorder (continued). "The detrimental role of neutrophils is also documented in 2 MS-related conditions: the neuromyelitis optica spectrum disorder (NMOSD) and the MOG Ab-associated disease (MOGAD)." (PMID 39656548, 2024). "Two other conditions known to cause ON are neuromyelitis optica spectrum disorder (NMOSD) and myelin oligodendrocyte glycoprotein (MOG)-immunoglobulin G (IgG) ON." (PMID 38618469, 2024). "Although less common, neuromyelitis optica spectrum disorder (NMOSD) and myelin oligodendrocyte glycoprotein antibody‐associated disease (MOGAD) were only diagnosed in matched‐only." (PMID 39435961, 2024). "In recent years, there has been increased awareness to differentiate the different ON phenotypes, namely, multiple sclerosis (MS), neuromyelitis optica spectrum disorder (NMOSD), and myelin oligodendrocyte glycoprotein antibody-associated disease (MOGAD)." (PMID 39741598, 2024). "The discovery of antibodies AQP4 and myelin oligodendrocyte glycoprotein (MOG) has expanded our understanding of the pathogenesis of neuromyelitis optica." (PMID 39238786, 2024). "Blood tests revealed positive neuromyelitis optica myelin oligodendrocyte glycoprotein antibodies after which diagnosis of neuromyelitis optica was made." (PMID 39310466, 2024). "MS, ON, neuromyelitis optica (NMO), optical coherence tomography (OCT), neuritis, NMOSD, MOG, magnetic resonance imaging (MRI), AQP4 and diagnostic criteria were high-frequency keywords." (PMID 38342798, 2024). "In recent years, there has been increased awareness regarding differentiating MS from other demyelinating ON phenotypes, namely, neuromyelitis optica spectrum disorder (NMOSD) and myelin oligodendrocyte glycoprotein antibody-associated disease (MOGAD)." (PMID 39741598, 2024). "Myelin oligodendrocyte glycoprotein (MOG) antibody-associated disease (MOGAD) is a demyelinating disorder, distinct from multiple sclerosis (MS) and neuromyelitis optica spectrum disorder (NMOSD)." (PMID 38783085, 2024). "Patients with multiple sclerosis (MS), myelin oligodendrocyte glycoprotein antibody associated disease (MOGAD) and neuromyelitis optica spectrum disorder (NMOSD) with disease onset before 18 years of age were included." (PMID 36761740, 2023). "Over 90% of the early reported pediatric cases with MOG-AD had classical acquired demyelinating syndromes of the CNS such as acute disseminated encephalomyelitis, optic neuritis, transverse myelitis, and neuromyelitis optica spectrum disorder." (PMID 37153594, 2023). "Pathogenic specificity is suggested by the absence of such findings in other demyelinating diseases, such as neuromyelitis optica and MOG antibody disease." (PMID 37676734, 2023). "Based on all this, the diagnosis of MOG antibody disease (MOGAD) with a neuromyelitis optica spectrum disorder (NMOSD)-like picture was made." (PMID 37547139, 2023). "Neuromyelitis optica spectrum disorder (NMOSD) and myelin oligodendrocyte glycoprotein antibody (MOG-IgG)-associated disorder (MOGAD) are antibody-mediated inflammatory disorders of the CNS distinct from multiple sclerosis (MS)." (PMID 37499337, 2023). "Patients with bilateral OD edema and abnormal visual function most likely have bilateral demyelinating optic neuritis, neuromyelitis optica spectrum disorder, and MOG, and require investigation with contrast-enhanced MRI of the brain and orbits." (PMID 37987292, 2023). "Most patients with neuromyelitis optica spectrum disorders (NMOSD) test positive for aquaporin-4 antibody (AQP4-IgG) or myelin oligodendrocyte glycoprotein antibodies (MOG-IgG)." (PMID 37740717, 2023). "Optic neuritis (ON) often occurs at the presentation of multiple sclerosis (MS), neuromyelitis optica spectrum disorders (NMOSD), and myelin oligodendrocyte glycoprotein (MOG) antibody-associated disease (MOGAD)." (PMID 36908609, 2023).
neuromyelitis optica spectrum disorder (continued). "Serum antibodies to myelin-oligodendrocyte glycoprotein (MOG) are biomarkers of MOG-IgG-associated disorder (MOGAD), a demyelinating disease distinct from both multiple sclerosis (MS) and aquaporin-4-IgG neuromyelitis optica spectrum disorder (NMOSD)." (PMID 36002821, 2022). "ON can be an isolated event or the initial symptom of central nervous system (CNS) autoimmune-mediated demyelinating diseases, such as multiple sclerosis (MS) or neuromyelitis optica (NMO) or myelin oligodendrocyte glycoprotein antibody disease (MOG-AD)." (PMID 35615385, 2022). "Clinical and CSF findings in patients with AQP4-IgG-positive neuromyelitis optica spectrum disorders (AQP4+NMOSD), MOG-IgG-associated disease (MOGAD), and multiple sclerosis (MS)." (PMID 36419536, 2022). "As described, TDLs are associated with MS, but they can occur in neuromyelitis optica spectrum disorders, and testing for AQP4-IgG and MOG-IgG is recommended." (PMID 35418930, 2022). "Serum antibodies to myelin-oligodendrocyte glycoprotein (MOG) are biomarkers of MOG-IgG-associated disorder (MOGAD), a demyelinating disease distinct from both multiple sclerosis and aquaporin-4-IgG neuromyelitis optica spectrum disorder." (PMID 36002821, 2022). "The clinical phenotype of disorders with MOG-antibodies far exceeds neuromyelitis optica and includes uni- or bilateral, isolated or recurrent ON, myelitis with or without ON, ADEM, brainstem and supra-tentorial lesions." (PMID 34097296, 2022). "Myelin oligodendrocyte glycoprotein (MOG) antibody has been associated with a wide range of neurological diseases, from neuromyelitis optica spectrum disorder to acute disseminated encephalomyelitis." (PMID 36447808, 2022). "Optic neuritis (ON) in neuromyelitis optica spectrum disorders (NMOSD) regularly leads to more profound vision loss compared to multiple sclerosis (MS) and myelin-oligodendrocyte-glycoprotein-antibody associated disease (MOGAD)." (PMID 36266394, 2022). "The research in the paediatric population correlated the anti-MOG antibodies with neuromyelitis optica (NMO) and transverse myelitis (TM) in monofocal and polyfocal forms." (PMID 35624969, 2022). "Serum aquaporin-4 (to evaluate for neuromyelitis optica spectrum disorder [NMOSD]§) and myelin oligodendrocyte glycoprotein (MOG) (to evaluate for MOG antibody–associated disease [MOGAD]¶) antibody test results were negative." (PMID 36136957, 2022). "Neuromyelitis optica spectrum disorders (NMOSD) and myelin oligodendrocyte glycoprotein antibody (MOG-IgG) associated disease (MOGAD) are autoimmune inflammatory demyelinating diseases of the central nervous system (CNS)." (PMID 35898513, 2022). "In neuromyelitis optica spectrum disorders (NMOSD) and myelin oligodendrocyte glycoprotein antibody-associated disease (MOGAD), neutrophils are found in CNS lesions." (PMID 36183103, 2022). "Spinal cord MRI abnormalities in patients with AQP4-IgG-positive neuromyelitis optica spectrum disorders (AQP4+NMOSD), MOG-IgG-associated disease (MOGAD), and multiple sclerosis (MS)." (PMID 36419536, 2022). "Characteristics of multiple scelorsis (MS), neuromyelitis optica spectrum disorder (NMOSD) and anti-myelin oligodendrocyte glycoprotein (MOG) associated disease (MOGAD)." (PMID 36401433, 2022). "Multiple sclerosis (MS), neuromyelitis optica spectrum disorder (NMOSD), and myelin oligodendrocyte glycoprotein antibody-associated disease (MOGAD) are major disease entities in this field." (PMID 35774780, 2022). "Optic neuritis (ON) is a frequent presentation at onset of multiple sclerosis (MS), neuromyelitis optica spectrum disorder (NMOSD), and myelin oligodendrocyte glycoprotein antibody-associated disease (MOGAD)." (PMID 36494385, 2022). "Neuromyelitis optica spectrum disorder (NMOSD) and myelin oligodendrocyte glycoprotein antibodies (MOG-Ab) associated disorders (MOGAD), have clinical features that overlap with MS which makes misdiagnosis possible." (PMID 33889068, 2021).
neuromyelitis optica spectrum disorder (continued). "Because of the overlapping clinical and MRI findings with MS, special attention would be devoted to neuromyelitis optica spectrum disorder (NMOSD) and myelin oligodendrocyte glycoprotein (MOG) antibody-associated disease (MOGAD)." (PMID 34867701, 2021). "IgG antibodies against MOG (MOG-Ab) overlap with neuromyelitis optica spectrum disorders (NMOSD) phenotype in adults." (PMID 34262784, 2021). "Neuromyelitis optica spectrum disorder (NMOSD) and myelin oligodendrocyte glycoprotein-antibody-associated disease (MOGAD) are antibody mediated CNS disorders mostly affecting the optic nerve and spinal cord with potential severe impact on the visual pathway." (PMID 35140707, 2021). "Neuromyelitis optica spectrum disorder (NMOSD) and myelin oligodendrocyte glycoprotein (MOG) antibody (Ab)-associated disease are also inflammatory CNS demyelinating disorders although clinically and pathologically they differ from MS and are far less common." (PMID 33804243, 2021). "All longitudinally extensive myelitis should entertain neuromyelitis optica, sarcoidosis, and anti-MOG encephalomyelitis in the differential." (PMID 34362398, 2021). "Testing for aquaporin-4 or myelin oligodendrocyte glycoprotein (MOG) antibodies should be performed in order to identify the initial manifestation of a neuromyelitis optica spectrum disorder (NMOSD) or MOG encephalomyelitis." (PMID 33283160, 2020). "Original publications on pain in neuromyelitis optica spectrum disorder (NMOSD) and myelin oligodendrocyte glycoprotein-antibody-associated disease (MOGAD) (listed in chronological order)." (PMID 33473247, 2020). "Classification of pain in neuromyelitis optica spectrum disorder (NMOSD) and myelin oligodendrocyte glycoprotein-antibody-associated disease (MOGAD)." (PMID 33473247, 2020). "Anti-MOG associated disorders can present as optic neuritis, monophasic ADEM or a neuromyelitis optica spectrum disorder (NMOSD)." (PMID 32231060, 2020). "It is commonly associated with MS, although it is also a common feature of myelin oligodendrocyte glycoprotein (MOG)-antibody disease and neuromyelitis optica spectrum disorders (NMOSD)." (PMID 33072106, 2020). "Within the CNS autoimmunity control cohort, autoantibodies against aquaporin 4 and high-titer Abs against myelin oligodendrocyte glycoprotein were, as expected, specific for neuromyelitis optica spectrum disorders." (PMID 30824481, 2019). "MRI characteristics can help in differentiating MOG-AD from other neuroinflammatory disorders, including multiple sclerosis and neuromyelitis optica." (PMID 30569382, 2019). "Given its clinical utility and the apparent higher incidence and prevalence of MOG Ab-associated demyelination compared to aquaporin-4 (AQP4) Ab-associated neuromyelitis optica spectrum disorders (NMOSD), requests for MOG Ab screening has dramatically risen." (PMID 31481127, 2019). "Anti-MOG antibodies have been reported in pediatric inflammatory demyelinative disorders and in a subset of patients with neuromyelitis optica." (PMID 31544855, 2018). "Reported prevalence rates of MOG-IgG seropositivity (based on cell-based assays) among patients with neuromyelitis optica spectrum disorder (NMOSD) and limited/related forms, according to phenotype and aquaporin-4 immunoglobulin G (AQP4-IgG) status." (PMID 29670575, 2018). "The MRZ reaction has been proposed as a highly specific (rule-in rather than rule-out) marker of MS, which discriminates well between MS and neuromyelitis optica and possibly also between MS and MOG encephalomyelitis." (PMID 28797088, 2017). "A subset of patients with neuromyelitis optica spectrum disorders (NMOSD) has been shown to be seropositive for myelin oligodendrocyte glycoprotein antibodies (MOG-IgG)." (PMID 27793206, 2016). "Antibodies against MOG (MOG-IgG) have been detected in a proportion of aquaporin-4 (AQP4)-IgG-seronegative patients with neuromyelitis optica spectrum disorder (NMOSD) phenotype." (PMID 27802824, 2016).
neuromyelitis optica spectrum disorder (continued). "Antibodies to myelin oligodendrocyte glycoprotein (MOG-IgG) have been suggested to play a role in a subset of patients with neuromyelitis optica and related disorders." (PMID 27788675, 2016). "Antibodies against myelin oligodendrocyte glycoprotein (MOG-IgG) are present in some neuromyelitis optica patients who lack antibodies against aquaporin-4 (AQP4-IgG)." (PMID 24685353, 2014). "We microinjected MOG-IgG, obtained from patients with neuromyelitis optica, into mouse brains and compared the results with AQP4-IgG." (PMID 24685353, 2014). "Transgenic mice that harbor both MOG specific T cells and MOG specific B cells develop a severe opticospinal syndrome and were proposed to mimic certain aspects of Devic's disease." (PMID 21264240, 2011). "The use of FCBA‐IF may result in underrecognition of both MOG antibody‐associated disease (MOGAD) and AQP4‐IgG seropositive neuromyelitis optica spectrum disorder (NMOSD)." (PMID 39901660, 2025). "This study aimed to evaluate the potential utility of glial fibrillary acidic protein (GFAP) and neurofilament light chain (NfL) as biomarkers of disease activity in AQP4-IgG-positive neuromyelitis optica spectrum disorder (NMOSD) and MOG antibody-associated disease (MOGAD)." (PMID 41155859, 2025). "Background/Objectives: Pediatric acquired demyelinating syndromes (ADSs) encompass a heterogeneous group of disorders, including multiple sclerosis (MS), MOG antibody-associated disease (MOGAD), and neuromyelitis optica spectrum disorder (NMOSD), with distinct clinical trajectories and prognoses." (PMID 40868427, 2025). "Multiple sclerosis (MS), aquaporin-4 antibody-positive neuromyelitis optica spectrum disorder (AQP4-Ab + ve NMOSD), and myelin oligodendrocyte glycoprotein-associated disease (MOGAD) are demyelinating diseases with differing pathophysiological processes and treatments." (PMID 40773034, 2025). "Comorbidities occur in aquaporin‐4 antibody‐positive neuromyelitis optica spectrum disorder (AQP4‐NMOSD), myelin oligodendrocyte glycoprotein antibody‐associated disease (MOGAD), and double seronegative NMOSD (DN‐NMOSD), potentially contributing to a less favorable disease course." (PMID 40485599, 2025). "The concept of neuromyelitis optica spectrum disorder (NMOSD) is changing, with a disease spectrum emerging that includes aquaporin 4 (AQP4) IgG-seropositive NMOSD, myelin oligodendrocyte glycoprotein (MOG) antibody-associated disease (MOGAD), and double-seronegative NMOSD." (PMID 40951029, 2025). "Neuromyelitis optica spectrum disorders (NMOSD) and myelin oligodendrocyte glycoprotein antibody-associated disease (MOGAD) are two distinct autoimmune central nervous system diseases, with overlapping clinical and radiological features but different pathophysiology and antibody profiles." (PMID 40481332, 2025). "MOG antibody-associated disease (MOGAD) is an autoimmune inflammatory disorder of the central nervous system (CNS), distinct from multiple sclerosis (MS) and aquaporin-4 antibody-positive neuromyelitis optica spectrum disorder (AQP4 Ab+ NMOSD)." (PMID 41393590, 2025). "Neuromyelitis optica spectrum disorders (NMOSD) and myelin oligodendrocyte glycoprotein-associated disease (MOGAD) are autoimmune disorders frequently accompanied by chronic, often neuropathic, pain, which significantly impacts the quality of life, sleep, and mental health." (PMID 40481332, 2025). "While the prototypical IDD is multiple sclerosis (MS), those include diseases such as neuromyelitis optica spectrum disorder (NMOSD), myelin oligodendrocyte glycoprotein (MOG) antibody-associated disease (MOGAD), acute disseminated encephalomyelitis (ADEM) and other rarer forms of CNS demyelination." (PMID 41441219, 2025).
neuromyelitis optica spectrum disorder (continued). "MOGAD is a demyelinating syndrome with the presence of antibodies against myelin oligodendrocyte glycoprotein, which is, next to multiple sclerosis and the neuromyelitis optica spectrum, one of the manifestations of the demyelinating process, more common in the pediatric population." (PMID 40137458, 2025). "Multiple sclerosis (MS), aquaporin-4 antibody positive neuromyelitis optica spectrum disorder (AQP4-Ab + ve NMOSD), and myelin oligodendrocyte glycoprotein antibody-associated disease (MOGAD) are three discrete autoimmune diseases of the central nervous system (CNS) that cause demyelination." (PMID 40773034, 2025). "Except for COVID-19-associated acute stroke, it is challenging to differentiate ADEM from various inflammatory and demyelinating disorders, such as multiple sclerosis (MS), myelin oligodendrocyte glycoprotein (MOG) antibody-associated disease and neuromyelitis optica spectrum disorder (NMOSD)." (PMID 40729267, 2024). "Since first approval in 1995, it is known that MMF is well-tolerated, with few severe complications, and is effective in many autoimmune disorders, including lupus, systemic sclerosis, myasthenia gravis, neuromyelitis optica, and myelin oligodendrocyte glycoprotein antibody disease." (PMID 39726762, 2024). "Myelin oligodendrocyte glycoprotein antibody-associated disease (MOGAD) is a rare autoimmune inflammatory disease of the central nervous system, (CNS) different from multiple sclerosis (MS) and neuromyelitis optica spectrum disorder (NMOSD)." (PMID 38835837, 2024). "Herein, we examine the differences in presentation, pathophysiology, and treatments of typical ON causes, like multiple sclerosis (MS), and atypical causes such as neuromyelitis optica spectrum disorder (NMOSD) and myelin oligodendrocyte glycoprotein (MOG)-immunoglobulin G (IgG) ON." (PMID 38618469, 2024). "Radiologically, optic neuritis is characterized by an acute swelling and enhancement of the optic nerve, usually monolateral, in a short segment if related to multiple sclerosis (MS) or bilateral and longitudinally extensive if related to neuromyelitis optica (NMO) or anti-MOG encephalomyelitis." (PMID 37882918, 2024). "Myelin oligodendrocyte glycoprotein antibody-associated encephalomyelitis (MOG-EM; also termed MOG antibody-associated disease, MOGAD) is the most important differential diagnosis of both multiple sclerosis and neuromyelitis optica spectrum disorders." (PMID 38609667, 2024). "Recently, because of the discovery of the auto antibodies immunoglobulin G to aquaporin-4 and myelin oligodendrocyte glycoprotein, the importance of optic neuritis in neuromyelitis optica spectrum disorder and myelin oligodendrocyte glycoprotein antibody disease has become more prominent." (PMID 38476197, 2024). "The most challenging aspect of the diagnostic process in ADEM is the differential diagnosis with a first attack of multiple sclerosis (MS), myelin oligodendrocyte glycoprotein antibody-associated disorder (MOGAD), or neuromyelitis optica spectrum disorder (NMOSD)." (PMID 39600741, 2024). "The main focus areas include regulatory B cells, ocrelizumab, neurodegeneration, demyelination, Epstein-Barr virus, laquinimod, myelin oligodendrocyte glycoprotein, gut microbiota, neuromyelitis optica, and dimethyl fumarate, highlighting the field’s knowledge structure and diversity." (PMID 39611149, 2024). "Certain demyelinating disorders, such as neuromyelitis optica spectrum disorder (NMOSD) and myelin oligodendrocyte glycoprotein antibody-associated disease (MOGAD) exhibit serum autoantibodies against aquaporin-4 (αAQP4) and myelin oligodendrocyte glycoprotein (αMOG)." (PMID 38580905, 2024).